IL1B (interleukin 1 beta)
Diseases named in the same sentence as IL1B in open-access papers (continued):
Sharing a sentence is not in itself a finding about the gene and the disease.
melanoma (continued). "In summary, our data demonstrated that DJ-1 deficiency can activate macrophages via NF-κB signaling to produce excess IL-1β, which is turn regulate MDSCs to build an immunosuppressive microenvironment for melanoma development." (PMID 25706411, 2015). "Earlier studies showed that a single dose of IL-1β is sufficient to significantly increase the number of lung metastases in a melanoma murine tumor model." (PMID 26327350, 2015). "IL-1β, IL-6, and IL-8, found in the melanoma tumor microenvironment, are important drivers of cell proliferation and melanoma progression." (PMID 25798946, 2015). "In patients, overexpression of IL-1β has been described in solid tumors, including breast, colon, lung, head and neck cancers, and melanomas." (PMID 24734023, 2014). "Elevated level of active IL-1β in melanoma cells has been shown to act in both paracrine and autocrine manners to promote tumor growth, angiogenesis, recruitment of macrophages and immune suppresser cells, invasion and metastasis." (PMID 24474192, 2014). "It’s well known that IL-1β is an important pro-inflammatory cytokine that promotes growth of colon cancer cells and enhances invasiveness and metastasis of B16 melanoma cells." (PMID 24223129, 2013). "Constitutively active NLRP3 inflammasome and IL-1β secretion were observed in late stage melanoma cells." (PMID 23065753, 2012). "For example, IL-1β promoted the adherence of human colorectal carcinoma cell lines and melanoma cell lines to endothelial cells in a dose-dependent manner." (PMID 22296757, 2012). "Harmine significantly inhibited the production of pro-inflammatory cytokines, namely TNF-α, IL-1β, IL-6 and GM-CSF by B16F-10 melanoma cell in culture." (PMID 21429205, 2011). "Upon co-culture with melanoma cells, the pro-angiogenic factors IL-8, IL-6, and IL-1β are up-regulated in neutrophils, synergistically promoting a microenvironment favorable for melanoma invasiveness." (PMID 24212647, 2011). "Targeting inflammatory cytokines, such as IL-1β, by siRNA in the melanoma-stimulated fibroblasts resulted in reduced melanoma cell invasion." (PMID 24212647, 2011). "Solid tumors in which IL-1β has been shown to be up regulated include breast, colon, lung, head and neck cancers, and melanomas, and patients with IL-1β producing tumors have generally bad prognoses." (PMID 17096856, 2006). "They found significantly increased staining for anti-Von Willebrand factor in melanoma cell-containing Matrigel plugs implanted into wild-type mice compared with IL-1β KO mice." (PMID 17096856, 2006). "Also, it was shown that ILs play a crucial role in the pathogenesis of melanoma by driving inflammation and expanding MDSCs, with IL-1β and the downstream IL-6/STAT3 axis being key contributors to this process." (PMID 40636453, 2025). "In melanoma, it is known to drive the production of Interleukin-1 beta (IL-1β), which sustains chemotherapy-resistant cells through an IL-1β/Interleukin-8 (IL-8)/C-X-C motif Chemokine Receptor 1 (CXCR1) signaling circuit, establishing a response that reinforces tumor growth and survival." (PMID 40445912, 2025). "Intriguingly, ERβ exhibits tissue-specific modulation of neutrophil function: while it recruits pro-lymphangiogenic neutrophils in LUAD (this study), it conversely induces IL-1β-dependent N1 neutrophils that suppress lung metastasis in triple-negative breast cancer and melanoma." (PMID 40739091, 2025). "We sought to investigate whether tumor-derived IL-1β could also protect melanoma cells from vemurafenib destruction." (PMID 41145465, 2025). "We would like to know whether IL-1β secreted by melanoma cells themselves also promote their own viability?" (PMID 41145465, 2025).
melanoma (continued). "Mechanistically, LINC01198 associates with TAOK1/2 to attenuate their phosphorylation and following enzymatic cascade, which potentiates nuclear transportation of YAP/TAZ to transcriptionally promote IL1B expression and enhance the viability of melanoma cells treated with vemurafenib." (PMID 41145465, 2025). "Mechanistically, LINC01198 directly associates with TAOK1/2 to inhibit TAOK1/2 phosphorylation and thereby elicits Hippo signaling through TAOK/LATS axis, which redistributes YAP/TAZ into nucleus and promotes the expression and secretion of IL-1β to support vemurafenib resistance in melanoma." (PMID 41145465, 2025). "1205Lu is a typical melanoma cell line with constitutive secretion of IL-1β." (PMID 40558540, 2025). "Likewise, IL-1β was confirmed to play a role in the metastasis of different tumour types to the lung, such as human colon carcinoma, human melanoma and renal carcinoma." (PMID 41440367, 2025). "This analysis revealed a more pronounced pro-inflammatory signature of NHKs (IL-1α, IL-1β, and IL-8) under the dynamic influence of melanoma cells compared to samples treated only with SPNs, indicating that bidirectional crosstalk amplifies the modification of the hosting tissue by melanoma cells." (PMID 40869222, 2025). "Although these findings could result from IL-1β secretion by immune cells earlier studies reported the expression of IL-1β by melanoma cells measured by PCR." (PMID 39858071, 2025). "Furthermore, during the metastasis of B16F-10 melanoma cells in mice, compound 4 dramatically reduced the serum levels of proinflammatory cytokines such IL-1β, IL-6, TNF-α, and GM-CSF." (PMID 38732642, 2024). "Validation of the pro-inflammatory genes including IL6, TNF, and IL1B revealed a significant increase in their expression in macrophages cultured with melanosomes derived from melanoma cells, keratinocytes, or fibroblasts as compared to naïve macrophages (Fig. EV4A)." (PMID 38719996, 2024). "Macrophages in melanoma produce IL-1β and act on fibroblasts." (PMID 38303024, 2024). "However, other studies have reported that NLRP3 inflammasome activation and the production of IL-1β and IL-18 can promote melanoma growth." (PMID 39769450, 2024). "Similarly, all three melanoma cell lines showed enhanced adhesion to IL-1β-stimulated pMBMECs compared to TNF-α-stimulated pMBMECs, although the data from the YUMM1.1 parental cell line were not significant." (PMID 37894438, 2023). "UA could significantly inhibit the production of TNF-α, IL-1β, IL-6 and GM-CSF gene expression and production by B16F-10 melanoma cell in culture in a dose-dependent manner." (PMID 36768978, 2023). "Th9 cells activated by IL-1β were shown to be highly effective against melanoma cells." (PMID 36611037, 2023). "Thus, more melanoma cells intercalated under the condition with compromised barrier properties of the IL-1β-stimulated pMBMECs." (PMID 37894438, 2023). "Enhanced levels of IL-6, TNF-α, and IL-1b in melanoma can trigger an immune response." (PMID 37895833, 2023). "Collectively, our findings indicate that melanoma‐derived IL‐1β might represent only a small fraction of the IL‐1β within the tumor microenvironment and targeting NLRP3 would affect primarily immune rather than tumor cells." (PMID 36707938, 2023). "Polymorphisms in the NLRP3 gene have been linked to the development of malignant melanoma, with an activation amplitude correlating with the stage of the disease; constitutive inflammasome activation is often found in late stages of melanoma, surrounded by elevated IL-1β level." (PMID 37891577, 2023). "To conclude, our work shows evidence of very low NLRP3 expression and IL‐1β secretion by melanoma cells and highlights the differences between cutaneous and uveal melanoma, providing data that may contribute to future melanoma translational research." (PMID 36707938, 2023).
melanoma (continued). "Further, the pro-apoptotic activity of sulforaphane on highly metastatic melanoma cells was demonstrated and associated with a significant caspases activation and down-regulation of pro-inflammatory cytokines such as TNF-α, IL-6, IL-1β, IL-12p40, and GM-CSF in murine melanoma cells." (PMID 36768978, 2023). "Here, we report that interleukin-1β (IL-1β) triggers the MMP-3 expression in canine melanoma cells." (PMID 36445856, 2022). "To confirm the contribution of NF-κB to MMP-3 mRNA expression mediated by IL-1β, we investigated whether IL-1β induced the mRNA expression of MMP-3 in p65/RelA or p105 knockdown melanoma cells." (PMID 36445856, 2022). "Here we show that feeding C57BL/6J mice with a non-obesogenic high fat high cholesterol diet (HFHCD) for two weeks to induce mild dyslipidemia, increases the pool of circulating Ly6Chi monocytes available for initial melanoma development, in an IL-1β-dependent manner." (PMID 36104342, 2022). "The Mitf− cells were shown to produce larger amounts of IL-1α and IL-1β, compared to Mitf+ cells; in addition, the supernatant of Mitf- melanoma cells reduced Mitf expression in positive cells via the signalling of IL-1R, which we previously found was significantly upregulated in the caerin group." (PMID 36497272, 2022). "Furthermore, it was suggested that expression and activation of the NLRP3 inflammasome in human melanoma cells correlate with malignancy and with spontaneous IL-1β secretion by late-stage melanoma." (PMID 36293159, 2022). "The activity of MMP-3 in the culture supernatant was increased in IL-1β-treated melanoma cells." (PMID 36445856, 2022). "Interestingly, these authors also observed higher levels of autophagy and protein secretion, such as CXCL8 and IL-1β, in metastatic melanomas in comparison to cells derived from primary lesions." (PMID 35008395, 2022). "However, depending on the stage, ASC has different roles in human melanoma: it acts as a tumor suppressor in primary tumors, but as a tumor promoter in metastatic melanoma, the latter via inflammasome-mediated IL-1β secretion." (PMID 36293159, 2022). "In melanoma, a high expression of this gene was correlated with the increased secretion of IL1β, CXCL8, LIF, FAM3C, and DKK3 in vitro, and metastatic melanoma patients with elevated tumor autophagy were shown to present higher levels of these proteins in their plasma." (PMID 35008395, 2022). "Therefore, understanding the precise function of each NF-κB subunit for IL-1β-evoked gene expression is important for developing new therapeutic strategies for melanoma." (PMID 36445856, 2022). "It has been shown that the crosstalk between CAF and TAM sustains tumor progression and that the generation of IL-1α and IL-1β by melanoma cells may promote this malignant interaction." (PMID 35406483, 2022). "We confirmed whether IL-1β induces the canonical NF-κB activation in canine melanoma cells by detecting the phosphorylation of p65/RelA and p105." (PMID 36445856, 2022). "Moreover, upregulation of IL1B has been reported in various solid tumors, including breast, colon, lung, melanoma, and others." (PMID 35163468, 2022). "The IL-1β-knockout mice did not develop tumors, but the wild-type mice developed melanoma, which caused deaths." (PMID 36288272, 2022). "IL-1β-deficient mice show no local tumor or lung metastases in a B16 melanoma model injected intravenously or intrafootpad." (PMID 35626056, 2022). "This includes a report describing the delivery of systemic IL-1β distant from the tumor site to effectively condition adoptively transferred T cell populations to generate improved anti-tumor immune responses in a B16 melanoma model." (PMID 34638239, 2021). "IL-1β was shown to promote the adhesion of cancer cells to endothelial cells in vitro, and administration of IL-1β to mice increased the number of lung and skeletal metastases, while reducing IL-1β activity in melanoma mouse models reduced tumor burden and metastases." (PMID 34207620, 2021).
melanoma (continued). "In this study, we investigate whether NLRP3-dependent IL-1β production observed in melanoma cells drives IL-6/STAT3 signaling and whether this influences MDSC activity." (PMID 34531850, 2021). "Notably, the use of combination IFN-γ and anti-PD-L1 antibody treatment to simulate CD8+ T cell activation-induced HSP70 secretion by these same human melanoma cell lines, while IL-1β remained undetectable." (PMID 34638239, 2021). "IL-1β has been reported to contribute to the development and progression of melanoma." (PMID 34211462, 2021). "Consequently, IL-1β-stimulated MAFs enhance the survival of MAPKi-treated melanoma cells in an ERK-independent manner, via NF-κB activation and bcl2 upregulation." (PMID 34067929, 2021). "Indeed, even when detected, the levels of IL-1β produced by melanoma cells are negligible relative to what is observed following the stimulation of various myeloid cell populations." (PMID 34638239, 2021). "LINC01116 can promote tumor proliferation and neutrophil recruitment through DDX5-mediated regulation of IL-1β in glioma cells; and melanoma-derived factors may alter the maturation and activation of differentiated tissue-resident dendritic cells." (PMID 34966411, 2021). "Unlike prior studies that have shown NLRP3-dependent release of IL-1β occurs in human melanoma cell lines and tissues derived from more advanced disease, we have been unable to induce IL-1β expression in human melanoma cell lines at significant levels with common NLRP3 stimuli." (PMID 34638239, 2021). "For instance, interleukin-1β (IL-1β) has been reported to be significantly expressed in melanoma." (PMID 32296574, 2020). "Knockout mice for IL-1β have reduced the angiogenesis and growth of melanoma tumors." (PMID 32796686, 2020). "Similarly, the concentration of IL-1β was much higher in melanoma patients than healthy donors (P < 0.001)." (PMID 32547321, 2020). "NLRP1 and NLRP3 are two key NLRP family members for IL-1β secretion in melanoma." (PMID 33396632, 2020). "In addition, tumor-associated macrophages secrete several cancer-stimulating molecules, such as IL-1, TNF-α, IFN-γ, angiotensin, COX-2, and IL-1β, to support the growth, angiogenesis, and metastasis of melanoma." (PMID 33171792, 2020). "Thus, melanoma-released factors enhance the responsiveness of macrophages toward IL-1β by altering the ratio of expression of activatory vs inhibitory receptor subunits." (PMID 32269145, 2020). "As an early response to VEM, IL-1β secretion from melanoma and stromal cells is reduced." (PMID 33396632, 2020). "Moreover, as demonstrated for melanoma cells, IL-1β, COX-2 and CCL2 were upregulated in bcl-2 overexpressing H1299 cells, while IL-8 was not affected and IL-17 was undetectable." (PMID 32269145, 2020). "In conclusion, our study demonstrated that IL-1β could enhance the stemness of squamous cell carcinoma and melanoma via activating Smad/ID1 pathway." (PMID 32547321, 2020). "Similarly, our work also indicated that Abx combined with the anti‐tumor drug DSF/Cu2+ had significantly inhibited the tumor growth in the melanoma‐bearing mice, accompanied by the reducing of inflammatory cytokines IL‐1β, IL‐6, and TNF‐α." (PMID 32750218, 2020). "In addition, inactivation of NLRP3 inflammasome has also been found to reduce IL-1β expression and halt development of melanoma." (PMID 33613533, 2020). "A similar result was obtained in IL-1β-treated B16 melanoma cells (P < 0.05)." (PMID 32547321, 2020). "In addition, we have also demonstrated that the expression of IL1B substantially varied among melanoma cell lines." (PMID 32466509, 2020). "It has been demonstrated that both primary and metastatic melanoma cells possessed activated inflammasomes that was associated with co-expression of ASC and NLRP3, whereas self-dependence of melanoma cells on IL-1β signaling was shown to increase with the stage of disease." (PMID 32340261, 2020).
melanoma (continued). "ATF4-mediated NLRP1 expression and IL-1β efflux may be the mechanistic basis for melanoma tumorigenesis and drug resistance via shaping the inflammatory tumor microenvironment." (PMID 33396632, 2020). "Hence, the IL-1β/miR155/MITF-M axis represent a novel mechanism by which melanoma cells escape the immune system in an inflammatory TME." (PMID 31557902, 2019). "Furthermore, when compared with classic Th9IL-4+TGF-β cells, Th9IL-4+IL-1β cells are less exhausted, exhibit cytotoxic T effector gene signature and tumor killing function, and exert a superior antitumor response in a mouse melanoma model." (PMID 30914642, 2019). "Melanoma cells and tumor-derived fibroblasts could express high levels of IL-1β, IL-6, TGF-β, and IL-23, which provide an optimal proinflammatory cytokine milieu for Th17 cells expansion." (PMID 30800130, 2019). "IL-1β also leads to the up-regulation of the NF-κB-regulated miR-155 in melanoma cell lines leading to reduced levels of the microphthalmia-associated TF (MITF-M), which drives the expression of many melanocyte-specific differentiation gene products that can be recognized by cytolytic T-cells." (PMID 31557902, 2019). "Notably, ubiquitination of endogenous BRAF was induced by TNFα or IL-1β treatment in both melanocytes and melanoma cells, while depletion of ITCH abrogated TNFα-stimulated BRAF ubiquitination." (PMID 31015455, 2019). "Moreover, the expression of BRAFV600E induced transcription of IL-1α and IL-1β in melanocytes and melanoma cell lines, which increased the suppression of proliferation and function of specific cytotoxic T cells in melanomas." (PMID 31775797, 2019). "Our results demonstrate that IL-1β produced by macrophages stimulates the metastatic potential of melanoma cells, such as migration and invasion properties, showing the essential role of myeloid cells in the production of IL-1β in tumor microenvironment through activation of the NLRP3 inflammasome." (PMID 31439870, 2019). "For example, in IL-1β-deficient mice, neither local tumors nor lung metastases developed after localized or intravenous inoculation with melanoma cell lines, which suggests that IL-1β-induced inflammation participates in the invasiveness of already existing tumor cells." (PMID 30767158, 2019). "The expression of IL-1β is elevated in a variety of cancers, including melanoma and breast cancer." (PMID 31558756, 2019). "They express high levels of IL-1β and IL-6, which may also contribute to Th17 cells expansion in melanoma." (PMID 30800130, 2019). "IL-1β-induced inflammation stimulates angiogenesis by promoting endothelial cell growth, tumor development, cancer cell invasiveness, and lung metastases of melanoma, breast, and prostate human cell lines." (PMID 31557902, 2019). "We observed that IL-1β transiently stimulated p65 phosphorylation in melanoma cells." (PMID 30562372, 2018). "Therefore, it is conceivable that phosphorylation of p65 is probably important for IL-1β-mediated COX-2 expression in melanoma cells, although further studies with specific phosphorylation sites are need." (PMID 30562372, 2018). "Therefore, it is most likely that p105 functions as the precursor of p50 in melanoma cells stimulated with IL-1β." (PMID 30562372, 2018). "Therefore, it is conceivable that IL-1β evoked the activation of NF-κB signaling in canine melanoma cells." (PMID 30562372, 2018). "Therefore, such a regulation of p105 appears to be involved in IL-1β-mediated COX-2 expression in melanoma cells." (PMID 30562372, 2018). "We also checked the effect of IL-1β (100 pM) on the cell viability of canine melanoma cells." (PMID 30562372, 2018). "Additionally, decreasing mRNA levels of IL-1α, IL-1β, and IL-18 further proved the negative regulation of CP on the melanoma inflammatory environment." (PMID 30149677, 2018). "Thus, it is conceivable that the NF-κB pathway as well as IL-1β-mediated COX-2 expression is a therapeutic target for melanomas." (PMID 30562372, 2018).